IL6 (interleukin 6)
Diseases named in the same sentence as IL6 in open-access papers (continued):
Sharing a sentence is not in itself a finding about the gene and the disease.
infection (continued). "Moreover, feeding with COL was able to suppress IL-6 production in S. typhimurium-infected animals, demonstrating powerful immunomodulatory activity during acute inflammation and infection." (PMID 37624306, 2023). "The combination of increased IL-6 at 6 h and reduced MCP-1 at 48 h was associated with infection." (PMID 37189111, 2023). "However, in our double immunofluorescent staining, the percentage of IL-6+GFAP+ cell was lower than IL-6+Iba1+ cell post-infection, which indicate that the pro-inflammatory cytokine, such as IL-6, was mainly derived from microglia." (PMID 37256871, 2023). "The absolute levels of TNF-α, IL-1β and IL-6 in P815 cells measured by ELISA confirmed the results from gene expression with RNA-seq analysis; thus, melatonin significantly reduced inflammatory cytokine levels at 12 h post-infection." (PMID 37200384, 2023). "IL-6 levels were significantly induced by the infection with Salmonella." (PMID 36768650, 2023). "Infection up-regulates IL6 protein and Il6 transcripts in dura fibroblasts." (PMID 37318981, 2023). "IL-6 is produced rapidly and transiently in response to infection and tissue injury." (PMID 37889917, 2023). "We decided to investigate whether the abortive development in mice of IL-6 Tg-PbANKA/LISP2 parasites could result in protection against secondary infection with WT PbANKA SPZ." (PMID 37143657, 2023). "The infection with S. Typhimurium significantly increased plasmatic IL-6 levels." (PMID 38003758, 2023). "After 24 h of infection, a significant increase of IL-6, IL-8 and monocyte chemoattractant protein (MCP)-1 in both variants could be observed." (PMID 38095608, 2023). "However, a rapid inhibitory response either directly by virus recognition or by ALI culture handling cannot be excluded, as mRNA levels of pro-inflammatory cytokines IL-6 and IL-8 were elevated directly after infection." (PMID 37112941, 2023). "In contrast, consistently high serum IL-6 concentrations suggest continuous production of IL-6 and may indicate unresolved insults, such as trauma or infection." (PMID 37214473, 2023). "IL-6 has been used as a potential biomarker to identify patients receiving anti-inflammatory therapies as it is secreted widely as a response to pathological states such as infection, inflammation and cancer." (PMID 38434639, 2023). "In addition, although IL-6 was shown to be decreased in the early stage of infection in B-cell-depleted mice, in the later stage of the disease, B-cell depletion led to an increase in IL-6." (PMID 37243059, 2023). "Previous study reported that infection by C. trachomatis in epithelial cells triggers release a range of cytokines that include IL-1α, granulocyte-macrophage colony-stimulating factor, (GM-CSF), IL-6, as well as IL-8." (PMID 36870960, 2023). "Several studies have reported a higher risk of IL-6 inhibitors, mostly tocilizumab, for serious infections, notably skin and soft tissue infections, compared with other biologic agents." (PMID 37367619, 2023). "IL-6 is one of the major biomarkers induced by RV-A16 infection in the lungs and airways." (PMID 36992456, 2023). "This was performed by collecting and analyzing the culture supernatants of lung explants infected by Fth LVS, Fth LVS ΔiglC, Fth A-660 and F-W12 24 h, 48 h and 72 h post infection to determine the levels of cytokines and chemokines (e.g. IL-1β, IL-6, TNF-α, IL-8, G-CSF, MCP-1, IP-10 and VEGF)." (PMID 37492528, 2023). "The IL-6 level was almost same at 12 h compared to 6 h post infection." (PMID 36707891, 2023). "On the other hand, the data presented here suggest that targeting ATF6α may be beneficial in selective contexts of inflammation that evoke an IL-12/IL-6 cytokine response, which may include infection with intracellular bacteria or certain autoimmune contexts." (PMID 37025177, 2023).
infection (continued). "Of the two S. parasuis strains, NN1 possessed a higher capacity to induce IL-6, TNF-α, and MCP-1 production by primary astrocytes throughout the experiment, and by BV2 cells at 8 h post-infection, whereas BS26 induced higher IL-6 production by BV2 cells from 18 h post-infection." (PMID 37111486, 2023). "Our results showed that IL-6 levels were maintained due to polymicrobial infection." (PMID 37621924, 2023). "We noticed an increase in IL6 level later time points post infection." (PMID 36707891, 2023). "GATA3 was positively correlated to IL6 during the whole period of infection." (PMID 37593762, 2023). "Furthermore, we observed that cells only infected with T. gondii and treated with rP21 increased IL-6 in relation to cells only infected with T. gondii (*P = 0.0269), while infection with T. gondii/T." (PMID 37915581, 2023). "Furthermore, MEFs and BMDMs isolated from IL-6−/− mice produced significantly increased virus yields after infection with JEV compared to cells derived from WT mice." (PMID 38053527, 2023). "On the other hand, MZ B cells may suppress inflammatory responses during the early stages of infection by producing IL-6, which inhibits the production of tumor necrosis factor-α and, therefore, the systemic inflammatory response." (PMID 37128298, 2023). "IL-6 serves as a crucial marker of systemic inflammation induced by highly virulent infections." (PMID 38203508, 2023). "It is currently unknown whether IL-6 inhibition might have similar benefits in other, severe infections, such as bacterial sepsis." (PMID 36716318, 2023). "Analysis of gene expression after infection with influenza, poly(I:C) or IL-6 injection in early neurodevelopment in rodent models indicated common patterns of change in gene expression relevant to neurogenesis and neuroprotection in the acute phase of infection." (PMID 37332846, 2023). "In turn, IL-6 is produced during infection and inflammation." (PMID 37760703, 2023). "There is evidence that HIV may increase bone turnover by itself and that it may be associated to an increase in cytokine expression, such as IL-6 and TNF during infection." (PMID 37753486, 2023). "IL-6 is a cytokine that contributes to host defense against various infections and tissue damage." (PMID 38018195, 2023). "The results of IL-6 levels showed that knockdown of PTX3 almost completely abolished the activation of the inflammatory response induced by the HA9801 infection, compared with the cells transfected with the non-specific siRNA (SiNC) and incubated with the PBS control." (PMID 36977278, 2023). "In addition, levels of hepatic interleukin-6 (IL-6) which is an essential factor indicating liver homeostasis, regeneration, infection defence and fine tuning of metabolic functions were also measured in all four studied groups of animals." (PMID 38152248, 2023). "Furthermore, our experiments demonstrate that HaCaT cells respond with a strong increase in IL-6 and IL-8 gene expressions after 24 h following infection with M. furfur compared to untreated cells." (PMID 36835509, 2023). "We also identified that Delta variant infection was associated with higher LDH, D-dimer, IL-6, and CPR compared with the Omicron variant, as these parameters were associated with more severe disease, and so this finding is consistent with the fact that Delta causes more severe illness than Omicron." (PMID 36979880, 2023). "Infection with virulent ASFV isolates often results in an exacerbated immune response, associated with elevated serum levels of pro-inflammatory cytokines (IL-1α, IL-1β, IL-6, TNF, CCL2, CCL5 and CXCL10)." (PMID 36680273, 2023). "Interleukin 6 is a pro-inflammatory cytokine produced in response to infection and tissue damage." (PMID 36873940, 2023). "Moreover, by 48 hours after infection every cytokine assayed was significantly increased in the ear after i.d. infection in contrast to just IFN-ɣ and IL-6 in the lung after i.n. infection." (PMID 37883420, 2023).
infection (continued). "The expression of IL-6, and IL-10 was highly reduced in Xiap−/− DCs during infection with ST-OVA." (PMID 37347786, 2023). "Low infection prevalence and intensities could also be the reason for low sensitivity of urinary IL-6 and IL-10 but further studies should shed more light on this." (PMID 37018184, 2023). "Moreover, CRP plays a crucial role in response to the host’s infection through NO release, phagocytosis, apoptosis and cytokine production, particularly IL-6 and TNF-α." (PMID 37237892, 2023). "The serum IL-6 concentration can serve as a potential marker of pathogenic infections in patients undergoing cardiac surgery with CPB and is thus useful for the early diagnosis of postoperative infections." (PMID 37189842, 2023). "In addition, control of the oral local infection is associated with a reduction in serum inflammatory markers including C-reactive protein (CRP) and interleukin-6 (IL-6)." (PMID 36243707, 2022). "In TB, IL-6 may play a pro-inflammatory role by stimulating cellular responses and inhibiting dissemination of the infection as suggested by studies that have demonstrated lethal TB infection after IL-6 knock-out in mice." (PMID 35025927, 2022). "In accordance, blocking Tlr7 and Tlr9 signalling significantly reduced IL-6 in both wt and Ifitm3−/− cells to similar levels following infection with MCMV, suggesting that Ifitm3-mediated regulation of these responses restricts MCMV-induced cytokine production." (PMID 36075894, 2022). "Additionally, this group found that early in infection, there was decreased IL-6 in the blood of C3aR−/− mice." (PMID 35925892, 2022). "LL-37 may also prepare astrocytes for infection by gearing them into a pro-inflammatory state with upregulated IL-1β and IL-6, but this inflammatory state must be reduced upon infection to prevent chronic inflammation and disease." (PMID 35634307, 2022). "The host's immune system releases a number of proinflammatory molecules during the blood infection stage in response to the parasite's presence, including IL-1, IL-6, IL-8, IL-12 (p70), IFN-γ, and TNF, all of which play a key role in limiting the parasite's growth and removal." (PMID 36510199, 2022). "In the liver, IL6 is an important stimulator of acute phase response and defense against infection." (PMID 36238273, 2022). "Similarly, E. coli 1587 infection dramatically stimulated the upregulation of IL-1β, IL-6, IL-10, and TNF-α mRNA transcription levels in mice colons 3 days post infection, but this phenomenon mostly diminished by 7 days post infection except for IL-6." (PMID 35399688, 2022). "This single-centre observational clinical pilot-study intended to investigate the role of selective biomarkers for inflammation and infection (PCT, ferritin, uB2MG, IL-6, IL-8, IL-10 and TNF-α) following TTPB and their association with post-operative complications such as infection and bleeding." (PMID 36154663, 2022). "IL-6 was abnormally elevated at 7–9 days after infection in our study." (PMID 36522677, 2022). "Another important cytokine that is produced in response to infection and tissue damage is IL-6." (PMID 36499338, 2022). "However, the pleotropic effects and the volatility over time of IL-6 make it intricate for blood concentration measurements to predict infection and determine prognosis." (PMID 36555941, 2022). "Resveratrol inhibits macrophage infiltration and IL-6 secretion during infection." (PMID 36339614, 2022). "Pro-inflammatory cytokines such as TNF-alpha and IL-6 are produced in response to infection." (PMID 35631351, 2022). "Another new attempt in our study was the application of IL-6 as the infection indicator of IBN." (PMID 36299571, 2022). "To determine if IL-6 was upregulated at later time points post-infection, we evaluated expression six days post-infection by qPCR, which showed a significant increase in IL-6 expression in HLOs infected with live SARS-CoV-2 compared to HLOs infected with a heat-inactivated virus." (PMID 36128218, 2022).
infection (continued). "There is a small number of transitions towards M0 and il6/il6* that increase in percentage, which may have a role in vivo by limiting the production of IL-12 as the infection progresses toward resolution." (PMID 35480895, 2022). "IL-6 also mediates tissue injury repair and acute phase response to infection." (PMID 36613892, 2022). "The most noticeable change in gene expression after infection with HAdV26 was seen for IL-6." (PMID 35458402, 2022). "Interestingly, both IL-6 and KC levels were significantly higher in Δpsmβ infected mice than WT strain infected mice, suggesting Δpsmβ infected mice had more severe systemic infection than WT infected mice." (PMID 36065015, 2022). "While infection with strain Nine Mile I rendered the cells partially refractory to re-stimulation with E. coli lipopolysaccharide, Cb30/14 exerted a selective suppressive effect which was restricted to IL-6 and TNF-α and spared IL-1β." (PMID 36558755, 2022). "Infection-induced gene expression levels of inflammatory cytokines such as Il6 and Tnf, type I (Ifna4 and Ifnb), and type III IFNs (Ifnl2/3) as well as ISGs such as Mx1, Isg15, and Stat1 peaked simultaneously with peak viral loads on day 2 p.i. in lungs and upper airways." (PMID 36129445, 2022). "The phage cocktail revealed anti-inflammatory effects when administered either 1 day after infection or 2 days after S. Typhimurium detection in feces, as measured by inhibition of the increase in levels of inflammatory response markers (IL-1β, IL-6, IFN-γ, IL-8, and IL-12)." (PMID 36211337, 2022). "In humans, increased levels of inflammatory cytokines such as IL-6 were found in older males with severe COVID whereas increased levels of anti-inflammatory cytokines like IL-10 were observed in older females 14 days post infection than in males." (PMID 36679892, 2022). "The infection of porcine parvovirus and Human parvovirus B19 also increased IL-6 expression." (PMID 35891451, 2022). "Inhibition of IL-6-signaling seems to be one of the more promising strategies for treatment of HF as well as infections but it has to be considered, that there is a lot of contradictory data so that a clear recommendation for immunomodulatory therapy cannot be given yet." (PMID 35548445, 2022). "IL-6 is expressed and released primarily by many different cells such as monocytes/macrophages, in the response to infections and tissue injury, via the binding of Toll-like receptor (TLR) family proteins to specific microbial molecules termed as pathogen-associated molecular patterns (PAMPs)." (PMID 36290585, 2022). "Indeed, it has previously been demonstrated that IL-6 is required for protection against several viruses including influenza and vaccinia viruses during the early stages of infection." (PMID 35529317, 2022). "Moreover, SIGNR1 blockade reduced NET deposition in the kidneys and lowered the levels of most inflammatory cytokines and chemokines including IL-6 and G-CSF, in the spleen, blood and kidneys 3 days post-infection." (PMID 35945238, 2022). "Thus, in order to investigate the possible mechanism underlying HAdV26-induced inflammation in the current study, we chose IL-6 as a representative inflammatory effector and further explored its expression in relation to HAdV26 infection." (PMID 35458402, 2022). "These authors reported tilmicosin decreased intracellular infection (p < 0.01), had a protection effect on the mammary epithelial cells reducing apoptosis after infection by 80% (p < 0.01), reduced reactive oxygen species (p < 0.01), IL-1β (p < 0.01), IL-6 (p < 0.01) and TNF-α (p < 0.05)." (PMID 36557690, 2022). "After infection, IL-6 triggers the release of CRP and peaks earlier than that of CRP." (PMID 36299571, 2022). "Interestingly, infection with either omicron, delta, or BavPat1 led to an upregulation of IP-10 and/or IL-6 expression in apical washes and/or basal medium compared to non-infected samples at 48 h.p.i.." (PMID 35632693, 2022).
infection (continued). "Moreover, in the PCLS infection model, Pla plays a vital role for the inhibition of the expression of the proinflammatory cytokines IL‐6, IL‐8, and TNFα during the first hours of infection." (PMID 34570407, 2022). "The increase in IL-6 levels observed here could have contributed to the host response in control of infection." (PMID 35337002, 2022). "Lactic acid decreases production of pro-inflammatory mediators (IL-6 and IL-8) in cultured cervical epithelium and lactate production by L. crispatus and L. gasseri has been shown to prevent infection by Chlamydia trachomatis, suppress growth of Escherichia coli, and Neisseria gonorrhoeae bacteria." (PMID 36434666, 2022). "We have also shown that IL-6 gene expression triggered by HAdV26 infection is NF-κB mediated." (PMID 35458402, 2022). "Particularly, IL-6 is considered a crucial cytokine for developing an antigen-specific humoral response during some infections, and IL-10 is an important anti-inflammatory cytokine that downregulates the production of pro-inflammatory cytokines and generally protects from systemic inflammation." (PMID 36497139, 2022). "However, not all groups maintained the original trend after 48 h, especially for IL-6 secretion level in the coinfection group, which was dramatically increased and higher than the coaggregation group after 48 h of infection." (PMID 35573793, 2022). "Our data suggest that the HAdV26 infection in epithelial cells could increase IL-6 expression through the NF-kB signaling pathway." (PMID 35458402, 2022). "Our data clearly demonstrated that PE_PGRS19 caused macrophage pyroptosis leading to the release of pro-inflammatory cytokines, and the pretreatment of macrophages with the pyroptosis inhibitor NSA blocked the increased transcript levels of il-6, il-1β, and il-18 induced by Ms_PE_PGRS19 infection." (PMID 36557726, 2022). "IL-6 has a pleiotropic function and is produced in response to tissue damage and infection." (PMID 36615820, 2022). "Expression of IL-6 mRNA transcripts was significantly upregulated during acute (5-fold; mean ± SE: 0.0002 ± 0.00005, p = 0.03) and chronic (2.5-fold; 0.0001 ± 0.00003, p = 0.006) compared to pre infection (0.00004 ± 0.000006)." (PMID 35281029, 2022). "IL-6 is a highly sensitive and specific biomarker for diagnosis of infections." (PMID 35144683, 2022). "Treg IL-10 was upregulated during late infection, perhaps to combat the coincided inflammatory cytokines (IL-1, IL-18, and IL-6) high levels and intense pathological lesions, protect the host from excessive tissue damage, and contribute to the Th1/Th2 balance and immune homeostasis." (PMID 36187827, 2022). "IL‐6, a pleiotropic cytokine that mediates a range of functions, including inflammatory responses, can be promptly and instantaneously generated upon infection or injury, resulting in the host defense through the activation of acute‐phase responses, hematopoiesis, and immunoreactivities." (PMID 36039646, 2022). "In the process of infection and tissue injury, IL-6 responds more rapidly than WBC and CRP." (PMID 35794529, 2022). "Therefore, there is an inverse association between vitamin A supplementation and plasma and fecal IL-6 concentrations in many infection conditions." (PMID 36496428, 2022). "During extracellular pathogen infection, naïve Th cells proliferate and differentiate toward the Th2 subtype, which functions through secreting various effector cytokines, including IL-4, IL-5, IL-6, IL-10, IL-13." (PMID 35241075, 2022). "It was shown that daily administration of probiotic (1 × 109 CFU) or placebo for three months significantly decreased the duration of infection-associated symptoms and allowed modulation of serum TNFα, CD163, G-CSF, ICAM-1, IL-6, IL-8, MCP-2, RAGE, uPAR, and PF4." (PMID 36317003, 2022). "In IBN treated by the Masquelet technique, IL-6 might also be used as a feasible indicator to decide whether the recurrent infection has been eliminated." (PMID 36299571, 2022).